RN7SKP69 (RN7SK pseudogene 69)
Gene: Miscellaneous RNA gene on chromosome 20 (17,576,206 to 17,576,510, reverse strand). Ensembl gene ENSG00000202260.
Homologues: Orthologues: chimpanzee 7SK (91% identical). Paralogues in human: RN7SKP171 (77% identical), RN7SKP71 (77% identical), 7SK (76% identical), RN7SKP79 (75% identical), RN7SKP176 (75% identical), RN7SKP255 (75% identical), RN7SKP9 (75% identical), RN7SKP203 (74% identical), RN7SKP124 (74% identical), RN7SKP211 (74% identical), RN7SKP133 (74% identical), RN7SKP151 (74% identical), and 283 more.